KLHL17 (kelch like family member 17)
Description:
Substrate-recognition component of some cullin-RING-based BCR (BTB-CUL3-RBX1) E3 ubiquitin-protein ligase complexes. The BCR(KLHL17) complex mediates the ubiquitination and subsequent degradation of GLUR6. May play a role in the actin-based neuronal function (By similarity).
Synonyms: AF
Tractability: Small molecule: it belongs to a druggable protein family.
Gene: Protein-coding gene on chromosome 1 (960,576 to 965,719, forward strand). Ensembl gene ENSG00000187961.
Subcellular location: Postsynaptic density; Synapse
Subcellular location (Human Protein Atlas): Nuclear bodies; Nucleoplasm
Gene Ontology:
Molecular function: protein binding; molecular adaptor activity; ubiquitin-like ligase-substrate adaptor activity
Biological process: actin cytoskeleton organization; proteasome-mediated ubiquitin-dependent protein catabolic process; protein ubiquitination
Cellular component: extracellular region; actin cytoskeleton; Cul3-RING ubiquitin ligase complex; cytoplasm; postsynaptic density; synapse
Genetic constraint (gnomAD): Loss-of-function variants: 63 observed, 60.68 expected, observed/expected ratio (o/e) 1.04, 90% interval 0.85 to 1.28. The synonymous counts are far from expectation, so gnomAD's model fits this gene poorly and the ratio says little. Missense variants: 1,052 observed, 875.74 expected, observed/expected ratio (o/e) 1.2, 90% interval 1.14 to 1.26. Synonymous variants: 584 observed, 381.1 expected, observed/expected ratio (o/e) 1.53, 90% interval 1.43 to 1.64.
Homologues: Orthologues: macaque KLHL17 (99% identical), dog KLHL17 (98% identical), mouse Klhl17 (98% identical), guinea pig KLHL17 (97% identical), rat Klhl17 (93% identical), chimpanzee KLHL17 (92% identical), pig KLHL17 (90% identical), zebrafish klhl17 (84% identical), tropical clawed frog klhl17 (78% identical). Paralogues in human: KLHL2 (44% identical), KLHL20 (44% identical), KLHL3 (43% identical), KLHL5 (39% identical), KLHL1 (39% identical), KLHL4 (38% identical), KLHL12 (35% identical), KLHL28 (34% identical), KEAP1 (34% identical), KLHL8 (34% identical), KLHL18 (34% identical), IPP (30% identical), and 42 more.
Diseases named in the same sentence as KLHL17 in open-access papers:
KLHL17 is named in the same sentence as 22 diseases in open-access papers, as found by Europe PMC text mining. Sharing a sentence is not in itself a finding about the gene and the disease. The quoted sentences say what the papers report.
infantile spasms (4 papers, 2018 to 2025). A rare epilepsy syndrome characterized by onset of epileptic spasms in infants between 2 and 12 months of age, and rarely up to 24 months. "Since KLHL17 has been linked to neurological disorders, including autism and infantile spasms, our study provides important insights into the functions of KLHL17 in neurons, representing a critical basis for discovering the etiology of KLHL17-related disorders." (PMID 37651441, 2023). "Human genetic analysis has suggested a link between KLHL17/AF and infantile spasms (IS), also known as West syndrome." (PMID 33256713, 2020).
neuroblastoma (2 papers, 2020 to 2023). Neuroblastoma (NB) is the most common solid, extracranial childhood tumor. "We expressed artificial miRNAs to knock down exogenous KLHL17/AF in mouse neuroblastoma Neuro-2A cells and endogenous KLHL17/AF in cultured neurons." (PMID 33256713, 2020). "In neuroblastoma Neuro-2A cells, immunoprecipitation of Myc-KLHL17 co-precipitated HA-SYNPO." (PMID 37651441, 2023).
autism (1 paper, 2023). Persistent deficits in social interaction and communication and interaction as well as a markedly restricted repertoire of activity and interest as well as repetitive patterns of behavior. "Both KLHL17 and SYNPO are F-actin-binding proteins linked to autism." (PMID 37651441, 2023).
developmental delay (1 paper, 2025). "Indeed, in several unrelated patients, deletion of different segments of chromosome 1p36 that include KLHL17 display a wide phenotypic spectrum, including developmental delay, mental retardation, and seizure/epilepsy." (PMID 40520989, 2025).
lung carcinoma (1 paper, 2020).
tumor (4 papers, 2017 to 2025). "We identified eight overexpressed and mutated tumor antigens with poor prognostic value of PRAD, including KLHL17, CPT1B, IQGAP3, LIME1, YJEFN3, KIAA1529, MSH5 and CELSR3." (PMID 34872584, 2021).
neurodevelopmental disorder (2 papers, 2022 to 2025). A behavioral and cognitive disorder with onset during the developmental period that involves impaired or aberrant development of intellectual, motor, or social functions. "Instead, we identified several rare, likely pathogenic variants in seven genes implicated in neurodevelopmental disorders: KLHL17, TDO2, TRRAP, EIF3F, ATP10A, DICER1, and CDH15." (PMID 35743796, 2022). "The finding may offer a new clue to investigate the molecular pathogenesis of KLHL17 gene in neurodevelopmental disorders." (PMID 40520989, 2025).
cancer (1 paper, 2018). A tumor composed of atypical neoplastic, often pleomorphic cells that invade other tissues. "Eight of these had decreased expression in cancer (KLHL3, KLHL4, KLHL13, KLHL14, KLHL29, KLHL30, KLHL32, and KLHL33) while four genes (ENC1, KLHL12, KLHL17, and KLHL35) had patterns of up-regulated gene expression." (PMID 30647843, 2018).
inflammation (1 paper, 2025). Aberrant reaction of the microcirculation characterized by movement of fluid and leukocytes from the blood into extravascular tissues. "We observed a positive enrichment of gene sets involved in inflammation or inflammation-related diseases in the group with the lowest KLHL17 expression." (PMID 40307206, 2025).
KLHL17 also shares sentences with these, for which no sentence is quoted: neurological disorders (2 papers); Anxiety (1); autism spectrum disorder (1); colon cancer (1); epidermoid carcinoma (1); gastric cancer (1); glioblastoma (1); Intellectual disability (1); melanoma (1); nasopharyngeal carcinoma (1); osteosarcoma (1); pancreatic cancer (1); prostate carcinoma (1).